ZEB2 (zinc finger E-box binding homeobox 2)
Diseases named in the same sentence as ZEB2 in open-access papers (continued):
Sharing a sentence is not in itself a finding about the gene and the disease.
melanoma (continued). "We previously showed that a switch from ZEB2 to ZEB1 expression is a poor prognostic factor in melanoma." (PMID 38519642, 2024). "To this end, we overexpressed ZEB1, leading to a decrease in E-cadherin expression and an increase in N-cadherin expression, or silenced SNAI2 or ZEB2 in melanoma cells in 2D cultures." (PMID 38398085, 2024). "In melanoma, we previously showed that, during melanoma progression, a switch in the EMT-TFs’ expression occurs, with a loss of ZEB2 and SNAI2 expression and the upregulation of ZEB1 and TWIST1 expression." (PMID 38398085, 2024). "ZEB1 notably binds to the promoter of ZEB2 and represses its expression in melanoma cells, while these two factors are co-expressed in mesenchymal cells." (PMID 38519642, 2024). "The transfection of miR-200c inhibitor resulted in increased ZEB2 and Vimentin and decreased expression of E-cadherin in the melanoma cancer stem cells from the control group." (PMID 38255297, 2024). "Zeb1 and Zeb2, both mesenchymal markers in the epithelial context, are inversely related in melanoma." (PMID 38247872, 2024). "Nonetheless, cell type-specific targets are particularly expected, given the antagonistic functions of ZEB1/ZEB2 in melanoma." (PMID 38519642, 2024). "Treatment of melanoma cell lines with PEBP and OMP resulted in the overexpression of miR-200c, which caused the negative regulation of ZEB2 and vimentin and up-regulated E-cadherin." (PMID 38255297, 2024). "ZEB2 3'-UTR acts as a ceRNA to regulate PTEN expression via miRNA-based regulation; moreover, ZEB2 attenuation (which commonly occurs in melanomas) activates the PI3K/AKT pathway by downregulating PTEN expression." (PMID 37771777, 2023). "The downregulation of Slug and Zeb2, and upregulation of Zeb1, Snail and Twist1 promote differentiation and metastasis in melanoma cells." (PMID 37181747, 2023). "In particular, Fra-1 (encoded by the gene FOSL1) is important for melanoma progression as its accumulation triggers the transcription factor switch that drives (partial)-EMT, downregulating Zeb2 and SNAI2 and directly upregulating Zeb1 at its promoter." (PMID 37181747, 2023). "In melanoma patients, ZEB2 deletion reduced their survival rate, which was verified in a mouse model of the disease." (PMID 36076302, 2022). "For the EMT transcription factors, both ZEB1 and ZEB2 showed overexpression in the RF models, especially ZEB2 expression in the melanoma-RF-FTMs." (PMID 36232952, 2022). "For example, a switch from ZEB2 to ZEB1 promotes the progression of melanoma, suggesting these two ZEB proteins function in an opposite manner under this condition." (PMID 35601657, 2022). "For instance, in a mouse model of melanoma, ZEB2 inhibited tumor metastasis, while ZEB1 drove tumorigenesis and progression." (PMID 36076302, 2022). "For instance, ZEB1 was shown to promote the progression of melanoma, whereas ZEB2 functions as a tumor suppressor to inhibit this process." (PMID 35601657, 2022). "A progressive loss of ZEB2/SNAIL2 and a gain in TWIST1/ZEB1 expression were observed along the transition from melanocytes to malignant melanoma." (PMID 32759677, 2020). "The ectopic expression of ZEB2/SNAIL2 promotes differentiation of melanoma cells, while ZEB2 knock-down results in a reduction of MITF expression and a switch from a differentiated to an undifferentiated melanoma cell phenotype." (PMID 32759677, 2020). "ZEB2-enforced expression in this mouse model also promotes growth of primary and metastatic tumors by favoring melanoma cell proliferation." (PMID 32759677, 2020). "In vivo ZEB2 overexpression and in vitro ZEB2 knock-down experiments show that ZEB2 drives the proliferative/differentiated melanoma gene signature while suppressing the invasive gene signature." (PMID 32796736, 2020). "Ectopic expression of ZEB2 can reverse the switch from a ZEB1high/MITFlow, invasive cell state to a ZEB2high/MITFhigh differentiated melanoma cell state." (PMID 32796736, 2020).
melanoma (continued). "ZEB2 silencing in mouse NRASQ61 melanoma cells decreases MITF, increases ZEB1, and induces proliferation defects." (PMID 32759677, 2020). "It is more likely that SLUG drives melanoma metastasis by promoting secondary tumour outgrowth in a similar manner as ZEB2 does." (PMID 32796736, 2020). "Ablation of ZEB2 in a NRASQ61K-driven mouse model delays melanoma initiation and attenuates nevus and melanoma outgrowth." (PMID 32796736, 2020). "Both MAPKi-resistant BRAFV600E-mutated melanoma cell lines and tumour biopsies obtained from human MAPKi-resistant BRAFV600E patients express high levels of ZEB1 but low levels of ZEB2 and MITF." (PMID 32796736, 2020). "Two research groups have independently shown that strong ZEB2/SLUG expression in primary melanomas is a positive prognostic factor for melanoma patients." (PMID 32796736, 2020). "In melanoma, ZEB1 and ZEB2 seem to be associated with antagonistic effects on TGF-β signalling, as is described in the following sections." (PMID 32796736, 2020). "Intra-tumor heterogeneity in the expression of ZEB2/ZEB1 was also documented in the NRASQ61 melanoma mouse model." (PMID 32759677, 2020). "A tumor-suppressive role for SNAIL2 and ZEB2 in melanoma was unexpected, although such an activity was suggested for Zeb2 mRNA through the activation of PTEN expression." (PMID 32759677, 2020). "ZEB2 drives MITF expression and is associated with a differentiated/proliferative melanoma cell state." (PMID 32796736, 2020). "Next to this, GLI family zinc finger 1 (GLI1) is proposed to be important for maintaining the invasive properties of melanoma cells in a ZEB2/MITF-independent manner but most likely ZEB1-dependent manner." (PMID 32796736, 2020). "The switch between Zeb2 and Zeb1 inside the melanoma was observed to be correlated with reduced expression of MITF and consequently with tumor progression." (PMID 31934531, 2019). "In agreement with the in vitro studies, in the four paired human melanomas where MerTK is overexpressed post-vemurafenib therapy, nuclear accumulation of Zeb2 is broadly present in resistant tumors." (PMID 29050198, 2017). "To investigate if Zeb2 can bind to these core enhancers, we performed a chromatin immunoprecipitation (ChIP) assay using overexpressed human Zeb2 in A375p melanoma cells." (PMID 29050198, 2017). "Mechanistically, BRAFi-induced activation of Zeb2 stimulates MerTK in BRAFV600 melanoma through mTORC1-triggered activation of autophagy." (PMID 29050198, 2017). "In murine mouse melanoma models, ZEB2 expression cooperates with BRAFV600E to promote melanogenesis." (PMID 29156643, 2017). "Another recent study analyzing a large cohort of patient samples also confirmed that low expression of ZEB2 corresponded to significantly reduced melanoma recurrence-free survival." (PMID 25763355, 2015). "Recent research showed that a reversible EMT-TF (transcription factor) reprogramming involving upregulation of ZEB1/TWIST1 paralleled by downregulation of SNAIL2/ZEB2 occurs in human melanoma." (PMID 25051363, 2014). "Reduction of ZEB2 mRNA expression commonly occurs in human melanomas and other cancers expressing low PTEN levels." (PMID 24523727, 2014). "The recent work on EMT-inducing transcription factors in melanoma leads to the idea that melanoma cells cycle between a differentiated and state (high levels of ZEB2 and SLUG) and a oncogenic invasive phenotype (high levels ZEB1 and TWIST)." (PMID 25538895, 2014). "A number of reports found significant roles for miRNA, ncRNA, or ceRNA in pathogenesis of melanoma; for example, ZEB2, a ceRNA for PTEN, upregulates expression of this tumor suppressor in melanoma." (PMID 24743024, 2014). "Based on human melanoma samples, a switch from ZEB2/SLUG to ZEB1/TWIST expression indicates malignant progression." (PMID 25538895, 2014).
melanoma (continued). "Point mutations or gene fusions in other genes (e.g., mutations in BRAF, KRAS, APC, and MET genes, or gene fusions in ZEB2‐ALK and SOX5‐RAF1 genes) may be associated with melanoma proliferation or melanoma progression in satellite nevi or LCMN." (PMID 41474606, 2026). "We found that silencing the SNAI2 and ZEB2 transcription factors, which behave as tumor suppressors in melanoma cells, significantly induced Tspan8’s endogenous expression at both the mRNA and protein levels in different melanoma cell lines." (PMID 38398085, 2024). "ZEB2 supports melanoma cell proliferation and differentiation by activating MITF expression." (PMID 38519642, 2024). "However, ZEB2 is relatively highly expressed in tumors such as leukemia, brain glioma, pancreatic adenocarcinoma, and melanoma." (PMID 35723302, 2022). "This is nicely exemplified in the case of cancer: inappropriate ZEB2 (over)expression correlates with bad prognosis of human early T-cell precursor leukemia, gastric cancer and melanoma, indicating that in healthy cells ZEB2 protein and activity need to be precisely controlled." (PMID 34356053, 2021). "Moreover, intra-tumor heterogeneity was observed within human primary melanoma lesions by immunohistochemical analyses: opposite gradients in the expression of ZEB2/SNAIL2 and TWIST1/ZEB1 were observed from superficial to deep sites." (PMID 32759677, 2020). "This intrinsic balance between ZEB1 and ZEB2 could prove to be a promising therapeutic target for melanoma patients." (PMID 32796736, 2020). "In particular, a reduced expression of ZEB2 and SNAIL2 in favour of an increased expression in ZEB1 and TWIST1 was linked to E-cadherin loss, increased invasion properties and poor clinical outcomes in human melanoma." (PMID 32858889, 2020). "Accordingly, aberrant expression of ZEB2 in melanoma cells may promote terminal differentiation and decreased tumorigenic capacity upon xenograft in nude mice, while intermediate levels of ZEB2 in transgenic mice would be compatible with proliferation." (PMID 32759677, 2020). "Finally, we will overview the current literature on ZEB1 and ZEB2 in the melanoma context and link this to the ‘phenotype-switching’ model of melanoma cellular plasticity." (PMID 32796736, 2020). "Therefore, ZEB2 protein levels should be evaluated to furthermore confirm the proposed ZEB2-independent functioning of GLI1 in melanoma invasion." (PMID 32796736, 2020). "Moreover, this switch from ZEB2/SNAIL2 to TWIST1/ZEB1 was a significant factor of poor prognosis for melanoma patients." (PMID 32759677, 2020). "In addition to FRA-1-driven oncogenic signaling, TGFβ was shown to promote the ZEB2/ZEB1 switch in melanoma cells." (PMID 32759677, 2020). "Moreover, the observed tumours in this model originated from melanoma cells that escaped ZEB2 ablation." (PMID 32796736, 2020). "Interestingly, the levels of miR-192-5p in CTLs co-cultured with hypoxic melanoma cells inversely correlated with their cytotoxic activity and ZEB2 mRNA expression, an immune-related and validated target of miR-192-5p." (PMID 33066331, 2020). "However, in melanomas harbouring mutant BRAF, Zeb2 is dynamically switched on/off and inversely associated with MAPK activation." (PMID 29050198, 2017). "Thus, in the context of mutant BRAF inhibition in melanoma, the activation of Zeb2/MerTK signaling plays an important role in mediating cancer cell survival and resistance." (PMID 29050198, 2017). "In melanocytes, the expressions of Snail2 and Zeb2 were found to be higher and act as oncosuppressor whereas Twist1 and Zeb1 promote neoplastic transformation of melanocytes and aberrantly reactivate in melanoma." (PMID 28137308, 2017). "Slug is strongly expressed in neural crest-delaminated melanoblasts, melanocytes and benign nevi and, together with another transcription factor of the zinc-finger E-box-binding like family (ZEB2), is regarded as a positive prognostic factor for melanoma patients." (PMID 28977999, 2017).
melanoma (continued). "In addition, we confirmed that vemurafenib downregulates the invasive melanoma marker ZEB1, and upregulates the proliferative melanoma marker ZEB2." (PMID 28545079, 2017). "In presence of BRAFi, Zeb2 is significantly activated in melanoma cells." (PMID 29050198, 2017). "As previously reported for their respective tumorigenic capacities, ZEB2 could therefore play an antagonistic function to ZEB1 in terms of resistance to treatment in melanoma." (PMID 27596438, 2016). "For example, AKT induces Snail and Zeb2 expression via the NFkB pathway leading to E-cadherin repression in squamous cell carcinoma cell lines and it will be interesting to investigate if this is also the case in melanoma." (PMID 25595898, 2015). "However, in light of a recent study showing that ZEB2 protein is oncosuppressive in melanoma, the functional role of ZEB2 is context and tumor type dependent." (PMID 24523727, 2014). "Interestingly, ZEB2 transcripts act as ceRNA towards miRNA targeting PTEN in melanoma cells." (PMID 35954450, 2022). "Overall, ZEB2/ZEB1 may not be associated with the acquisition of a given cell state but may regulate reversible transitions of melanoma cell state in a dynamic manner." (PMID 32759677, 2020). "Interestingly, miR-192-5p levels on CTLs after co-culture with hypoxic melanoma cells were inversely correlated with the cytotoxic activity of T cells and with ZEB2 mRNA expression, a validated immune-related target of miR-192-5p, which is also observed in vivo." (PMID 33066331, 2020). "Indeed, ZEB2 and SNAIL2 are expressed in normal adult melanocytes, and a switch in EMT‐TFs expression, characterized by a loss of ZEB2 and SNAIL2 and an upregulation of ZEB1 and TWIST1, occurs during melanoma progression." (PMID 27596438, 2016). "The finding of the mRNA of oncogene ZEB2 suppressing melanoma development suggests that a traditional protein-coding mRNA may not only function as a non-coding RNA, but also the role of the protein may be different or in opposition to that of the non-coding RNA." (PMID 26872371, 2016). "Besides the effects of ZEB2 expression on MITF and cellular plasticity, ZEB2 might also have a tumor-suppressive role due to its modulation of PTEN in a complex RNA-regulatory network in melanoma." (PMID 25538895, 2014). "This cancer involved a ZEB2:ALK fusion gene, as well as amplifications of parts of chromosomes 6p and 11q that are frequently seen in melanoma in addition to other chromosomal aberrations." (PMID 39755235, 2025). "Evidence shows the ZEB2 to ZEB1 switch drives invasion and furthers the dedifferentiation of melanoma cells." (PMID 38426087, 2024). "The attenuation of ZEB2 commonly results in activation of the PI3K/Akt pathway, a downstream target of PTEN, thereby enhancing cell transformation in human melanoma." (PMID 37371832, 2023). "For example, ZEB1 promotes the initiation and metastatic progression of melanoma which is supported by TWIST1, whilst ZEB2, supported by SNAI2, acts as a melanoma tumour suppressor." (PMID 35278142, 2022). "It has been proven that following the activation of the NRAS / BRAF pathway in melanoma, genes promoting cell proliferation such as SNAIL2 and ZEB2 are replaced by those regulating the migration such as ZEB1 and TWIST1." (PMID 35820816, 2022). "Therefore, while ZEB1 and TWIST1 harbor oncogenic activities in melanoma, ZEB2 and SNAIL2, which are expressed in normal melanocytes and are required for their proper differentiation, they may act as oncosuppressive proteins in this specific neural crest-derived lineage." (PMID 32759677, 2020). "In melanoma context, the roles of ZEB1 and ZEB2 seem to be antagonistic and to function in line with the “phenotype-switching” model." (PMID 32796736, 2020). "In contrast, ectopic expression of ZEB2 and SNAIL2 in melanoma cells decreases tumor formation in nude mice." (PMID 32759677, 2020).
melanoma (continued). "For example TWIST1 and ZEB1 increase the metastatic potential of melanoma cells whereas SNAI2 (SLUG) and ZEB2 decrease it." (PMID 29432466, 2018). "In line with Denecker, which showed ZEB1 and ZEB2 inverse modulation and the presence of ZEB2 as a positive prognostic factor for melanoma patients, we observed the SCD5-dependent up-regulation of ZEB2 paralleled by reduced amounts of ZEB1." (PMID 29484133, 2018). "Knocking down of Zeb2 leads to significant downregulation of MITF and concomitant upregulation of Zeb1, Vimentin and Fibronectin resulted in enhanced melanoma progression." (PMID 28137308, 2017). "Normal epidermal melanocytes from a melanoma patient expressed low ZEB1 and high ZEB2 expression, whereas the melanoma cells at deep sites from the same patient had high ZEB1 and low ZEB2 levels." (PMID 25763355, 2015). "The cordycepin treatment downregulated the expression of ZEB1, HMGA2 and TWIST1 by more than 50% but had minimal effects on ADAM9, RAC1, SALL4, CTNNB1, ZEB2 and YES1 in these two melanoma cell lines." (PMID 25868853, 2015). "In melanoma, overexpression of ZEB1 and TWIST1 with low expression of ZEB2 significantly shortens metastasis-free survival." (PMID 26515895, 2015). "mRNA expression levels of these markers of melanoma cell states were consistently modified with the protein, except for ZEB2 mRNA which was not modified, consistent with previous reports, suggesting an additional post-translational regulatory mechanism." (PMID 38519642, 2024). "Interestingly, while some ZEB1 peaks were conserved in MDA-MB-231, peaks in ZEB2, SOX10 and NGFR were only found in melanoma cells." (PMID 38519642, 2024). "Melanoma CAF subpopulations usually include iCAFs and myCAFs, however, a number of other unique clusters have been put forth including, distinct ECM and contractile CAFs in, Wif1 and Zeb2 subpopulations, and matrix and RGS5." (PMID 38525245, 2024). "In contrast, melanoma cell invasion was driven by high ZEB1 and low ZEB2 expression levels." (PMID 38139138, 2023). "The expressions of ZEB2 and SNAI2 fluctuated across the melanoma clusters." (PMID 35884783, 2022). "Moreover, the depletion of ZEB2 activates the AKT pathway and enhances oncogenic cell transformation of melanoma." (PMID 35954450, 2022). "Our team demonstrated that ZEB2 and SNAIL2 are highly expressed in MITFhigh proliferative melanoma cells, whereas decreased expression of ZEB2 and SNAIL2 and aberrant activation of ZEB1 and TWIST1 promoted phenotype switching towards an invasive, dedifferentiated and MITFlow phenotype." (PMID 35432344, 2022). "First, a ZEB2-MITF-ZEB1 axis has been identified in melanogenesis and melanoma progression." (PMID 34356053, 2021). "However, in melanoma, an intrinsic balance between ZEB1 and ZEB2 seems to determine the cellular state by modulating the expression of the master regulator of melanocyte homeostasis, microphthalmia-associated transcription factor (MITF)." (PMID 32796736, 2020). "Indeed, ZEB1 and TWIST1 have been shown to downregulate MITF whereas SNAIL2 or ZEB2 induce MITF expression, demonstrating that these EMT-TFs act as key players in melanoma phenotype switching." (PMID 32858889, 2020). "It is assumed that melanoma can metastasize faster than other malignant skin tumors, being more aggressive because normal melanocytes possess from the start elements which contribute to EMT, such as vimentin or some transcription factors (SNAIL2, ZEB2)." (PMID 31934531, 2019). "Basically ZEB2 is expressed in normal melanocyte, while ZEB1 is highly expressed in melanoma." (PMID 31275381, 2019). "In melanoma, the difference between ZEB1 and ZEB2 has been studied well." (PMID 31275381, 2019). "ZEB2 is a member of the zinc finger homeodomain enhancer-binding protein (ZEB) family, and it is both necessary and sufficient to repress ECAD transcription and trigger the EMT process in melanoma." (PMID 26010068, 2015).